ENSG00000279284 ( gene)
Diseases named in the same sentence as ENSG00000279284 in open-access papers (continued):
Sharing a sentence is not in itself a finding about the gene and the disease.
pancreatic cancer (8 papers, 2014 to 2025). "DNA cross‐link repair 1B (DCLRE1B), a 5′‐to‐3′ exonuclease, a DNA repair gene, is upregulated in pancreatic cancer, promotes the proliferation of pancreatic cancer cells, and is associated with poor prognosis." (PMID 40448344, 2025). "For example, miR-130a is upregulated in oral squamous cell carcinoma and suppresses expression of TSC1, a tumor suppressor gene, and an miR-301a inhibitor suppresses pancreatic tumor growth in a xenograft model." (PMID 34830336, 2021). "In conclusion, our present study demonstrated that FUT11 is a new hypoxia related gene, and is overexpressed in pancreatic cancer tissues and related to poor prognosis of pancreatic cancer patients." (PMID 34221996, 2021).
cervical cancer (7 papers, 2015 to 2024). A primary or metastatic malignant neoplasm involving the cervix. "ST20, also known as HCCS-1, exhibits downregulated expression in a variety of human malignancies, potentially fulfilling the role of a tumor suppressor gene by activating apoptotic signaling pathways, thereby restraining the progression of cervical cancer." (PMID 39309810, 2024). "It is well known miR-653-5p may target chromosome 11 open reading frame 30, and miR-653-5p acts as a tumor suppressor gene in cervical cancer." (PMID 34866540, 2021).
glioblastoma (7 papers, 2012 to 2024). The most malignant astrocytic tumor (WHO grade IV). "Remarkably, ERRFI1 is lauded as a tumor suppressor gene of glioblastomas, whose high expression can diminish the migration of glioblastoma cells." (PMID 33117083, 2020). "Here, we propose that JMJD3 acts as a tumor suppressor gene in glioblastoma multiforme." (PMID 23236496, 2012). "QKI and PARK2 are located within the same minimal common region on chromosome 6q26-27; PARK2 is a tumor suppressor gene in GBM (glioblastoma), and has an additive effect with QKI in tumor suppression." (PMID 39479357, 2024). "It is not clear why iron-regulating gene function fails to differentiate long- and short-term survivors in glioblastoma multiforme, especially considering the evidence that polymorphisms in a single iron-regulatory gene, HFE, may decrease survival in GBM." (PMID 27898674, 2016).
esophageal cancer (6 papers, 2013 to 2026). A primary or metastatic malignant neoplasm involving the esophagus. "In summary, miR-139-5p was identified as a tumor suppressor gene associated with the risk for esophageal cancer, and a novel mechanism of regulation of NR5A2 protein by miR-139-5p was reported." (PMID 24204738, 2013). "The results suggest that miR-139-5p functions as a tumor-suppressor gene involved in esophageal cancer development." (PMID 24204738, 2013). "Many studies suggested that SPINK7 may function as a tumor suppressor gene regulating the protease cascades during carcinogenesis and invasion of esophageal cancer." (PMID 29301256, 2018).
Obesity (6 papers, 2015 to 2024). Accumulation of substantial excess body fat. "We report that deletion of the innate immunity antibacterial gene Nod2 abolishes this resistance, as Nod2−/− BALB/c mice developed HFD-dependent obesity and hallmark features of metabolic syndrome." (PMID 28373658, 2017). "Previously, it was shown that whole-body Ahr knockout mice on HFD have increased transcript levels of the thermogenic uncoupling gene Ucp1 in BAT as compared wild type mice, potentially explaining how Ahr knockout could protect against HFD induced obesity." (PMID 32730300, 2020).
lung adenocarcinoma (5 papers, 2022 to 2025). A carcinoma that arises from the lung and is characterized by the presence of malignant glandular epithelial cells. "Glucosamine 6-phosphate N-acetyltransferase (GNPNAT1), which serves as a critical enzyme in hexosamine biosynthetic pathway (HBP), has been identified as a metastasis-associated gene and is upregulated in lung adenocarcinoma (LUAD)." (PMID 39062049, 2024). "However, the expression of GPM6A decreases in lung adenocarcinoma, liver cancer, thyroid cancer, and so forth as the tumor progresses, indicating that it may be a tumor suppressor gene." (PMID 39957375, 2025).
thyroid cancer (5 papers, 2020 to 2025). "Previous studies have elucidated the dual role of UBE2C in thyroid cancer (THCA) as both a tumor suppressor gene and an oncogene." (PMID 38577722, 2024).
autism (4 papers, 2009 to 2024). Persistent deficits in social interaction and communication and interaction as well as a markedly restricted repertoire of activity and interest as well as repetitive patterns of behavior. "We found a significant association between autism and a coding variant in the seizure-related gene SEZ6L2 (12/1106 autism vs. 3/1161 controls; p = 0.018)." (PMID 19242545, 2009). "Regarding IFI16, an anti-inflammatory gene, we found a highly significantly reduced expression in the NSCs (75%) but a significantly increased expression in the astrocytes (>45%) of patients with autism vs. controls." (PMID 38994948, 2024). "This is consistent with the traditional view of Top2a’s role as a “housekeeping” gene with no known selectivity for autism risk genes, although a Top2a ChIP-seq experiment in neurons or developing brains of zebrafish will be needed to confirm this finding." (PMID 36417527, 2022). "Human sex differences in autophagy are prominent in the brain and other tissues, with sex-differential effects from genetic variation also found in the autophagy-regulating gene ADNP (Activity-Dependent Neuroprotective Protein), which, like AMBRA1, affects autism and schizophrenia risk and traits." (PMID 31687209, 2019).
brain tumors (4 papers, 2010 to 2018). "Based on previous reports, miR-34a is considered a putative tumor suppressor gene in various types of cancers including brain tumors." (PMID 25551588, 2014). "In addition, CDKN3 has been proposed to be a tumor suppressor gene of brain tumors and of mitosis control." (PMID 26372210, 2015). "There was also a tendency for association between the 2251G minor allele of the nucleotide excision DNA repair gene XPD in both homo- and heterozygous forms and an increased chance of developing a brain tumor ( p = 0.084, OR = 1.48, 95% confidence interval 0.97–2.27)." (PMID 22649665, 2010). "In the context of brain tumors, expression of BECN1, a specific autophagy gene, is lower in GBMs compared to lower grade astrocytomas and normal brain tissues." (PMID 29692710, 2018).
cholangiocarcinoma (4 papers, 2020 to 2025). A carcinoma that arises from the intrahepatic biliary tree (intrahepatic cholangiocarcinoma) or from the junction, or adjacent to the junction, of the right and left hepatic ducts (hilar cholangiocarcinoma). "ARID1A, a chromatin remodeling gene, is implicated in multiple malignancies including HCC and cholangiocarcinoma." (PMID 41146957, 2025). "In this report, we mined the published cholangiocarcinoma transcriptome data set (GSE26566), compared it with the ubiquitination-associated gene (GO:0016567), and identified that UBE2C was highly expressed in cholangiocarcinoma tumor tissue." (PMID 38102624, 2023). "Reviewing the literatures, we found that APOB played a role as an oncogene in many tumors, but not as a potential tumor suppressor gene in cholangiocarcinoma as we found." (PMID 33954113, 2021).
colorectal tumor (4 papers, 2016 to 2022). "This association between rs2282151 and CRC is probably mediated by the expression of the inflammatory-related gene HSP90AB1, which is upregulated in colorectal tumor tissues." (PMID 27756247, 2016).
Lynch syndrome (4 papers, 2009 to 2025). An autosomal dominant hereditary neoplastic syndrome characterized by the development of colorectal carcinoma and a high risk of developing endometrial carcinoma, gastric carcinoma, ovarian carcinoma, renal pelvis carcinoma, and small intestinal carcinoma. "MSH6, a key DNA mismatch repair gene, is highly expressed in PGCs,31,41 and its mutations are linked to Lynch syndrome." (PMID 39999848, 2025). "It has been proposed that one additional mismatch repair gene, mutL homolog 3 (MLH3), also plays a role in Lynch syndrome predisposition, but the clinical significance of mutations in this gene is less clear." (PMID 19466295, 2009).
neuroblastoma (4 papers, 2015 to 2025). Neuroblastoma (NB) is the most common solid, extracranial childhood tumor. "Exostosin-like glycosyltransferase 1 (EXTL1), a member of the EXT family of tumor suppressor genes, was identified as a candidate neuroblastoma tumor-suppressor gene." (PMID 40660393, 2025). "Here we also evaluated whether CASZ1a interacts with another NuRD subunit CHD5, which is a neuroblastoma tumor suppressor gene." (PMID 26296975, 2015).
squamous cell carcinoma (4 papers, 2008 to 2024). A carcinoma arising from squamous epithelial cells. "The role of miR124 has been resembled to a tumor suppressor gene which is mediated by inhibition of SPHK1 gene in squamous cell carcinoma." (PMID 39315290, 2024). "In summary, the action of NOTCH1 in the development of squamous cell carcinomas, its role as both a tumor suppressor gene and as a protooncogene, is not yet fully understood." (PMID 37008245, 2023). "VILIP-1, a member of the neuronal Ca++ sensor protein family, acts as a tumor suppressor gene in an experimental animal model by inhibiting cell proliferation, adhesion and invasiveness of squamous cell carcinoma cells." (PMID 18301774, 2008).
bladder cancer (3 papers, 2009 to 2015). "Rho GDP dissociation inhibitor 2 (RhoGDI2) has recently been identified as a metastasis suppressor gene in models of bladder cancer." (PMID 24137348, 2013). "In breast, lung, prostate and bladder cancer, WIF1 expression was found to be frequently downregulated, suggesting it might represent a tumor suppressor gene." (PMID 19570204, 2009).
bladder tumor (3 papers, 2012 to 2020). "Approximately 76% of all primary bladder tumors display mutations in at least one chromatin regulatory gene." (PMID 31627336, 2019). "APOE has been shown to interact with the transitional epithelial response gene (TERE1), a tumor suppressor gene, in bladder tumor cells, resulting in increased cell turnover and resistance to apoptosis." (PMID 23094052, 2012). "In conclusion, our study demonstrated for the first time that TET1 may function as a tumor suppressor gene in UBC and AJAP1 plays a crucial role in TET1 suppression of bladder tumor growth through modulation of the Wnt/β-catenin signaling, affecting its downstream target genes." (PMID 32528872, 2020).
endometriosis (3 papers, 2017 to 2025). The growth of functional endometrial tissue in anatomic sites outside the uterine body. "DDR2 is a key hypoxia‐related gene in endometriosis and a promising diagnostic and therapeutic biomarker." (PMID 41424583, 2025).
kidney cancer (3 papers, 2013 to 2020). Primary or metastatic malignant neoplasm involving the kidney. "Our study indicates that TRIM33 plays a role as a tumor suppressor gene in ccRCC and may become a potential target and prognostic marker for kidney cancer treatment in the future." (PMID 32908919, 2020).
liver cancer (3 papers, 2005 to 2025). An epithelial or non-epithelial malignant neoplasm that arises from the liver. "Whereas opposite evidence of YTHDC2 as a tumor suppressor gene is also reported in liver cancer, covering the underneath mechanisms a heterogeneous veil." (PMID 34497675, 2021).
oral squamous cell carcinoma (3 papers, 2021 to 2022). "Cisplatin-activated autophagy promotes the expression of circ-PKD2, which plays a role as a tumor suppressor gene in the proliferation, migration, and invasion in oral squamous cell carcinoma (OSCC)." (PMID 35220397, 2022).
renal carcinoma (3 papers, 2022). A carcinoma arising from the epithelium of the renal parenchyma or the renal pelvis. "Importantly, the overexpression of KCNJ15 was shown to significantly inhibit the proliferation, migration, and colony formation of renal cancer cells, arrest the cell cycle and induce cancer cell apoptosis, which may be a tumor suppressor gene in renal cancer." (PMID 36389709, 2022). "We infected the human renal carcinoma cell line iSLK with a modified version of the BAC16 KSHV genome containing a far-red fluorescent protein (mIFP2) driven by the promoter of the viral late gene K8.1 as well as a constitutive EGFP." (PMID 35041709, 2022).
renal cell carcinoma (3 papers, 2019 to 2022). "In addition, IDUA is a novel glycolysis-related gene that is associated with the immune microenvironment in renal cell carcinoma." (PMID 35945500, 2022).
schizophrenia (3 papers, 2017 to 2019). A major psychotic disorder characterized by abnormalities in the perception or expression of reality. "Human studies of schizophrenia are now reporting a previously unidentified genetic convergence on postsynaptic signaling complexes such as the activity-regulated cytoskeletal-associated (Arc) gene." (PMID 28979198, 2017). "In addition, mRNA levels of myelin-associated oligodendrocyte basic protein (MOBP), an oligodendrocyte-associated gene, are increased in Pfc white matter in schizophrenia patients." (PMID 29163023, 2017).
virus infection (3 papers, 2017 to 2025). "Additionally, the expression of the JA-regulated defense gene PI-II in tomato plants was repressed by virus infection." (PMID 28373670, 2017).
astrocytomas (2 papers, 2018 to 2019). "In contrast, in astrocytomas IDH-wildtype the deletion of PTEN is a factor of poor prognosis, as expected, since this is a tumor suppressor gene." (PMID 31623593, 2019).
Bloom syndrome (2 papers, 2013 to 2022). Bloom syndrome (BSyn) is a rare chromosomal breakage syndrome characterized by a marked genetic instability associated with pre- and postnatal growth retardation, facial sun-sensitive telangiectatic erythema, increased susceptibility to infections, and predisposition to cancer. "There are five members of RecQ, which are RECQL (also called RECQL1), BLM (Bloom’s syndrome gene), WRN (Werner’s syndrome gene), RECQL4, and RECQL5 with unique biochemical functions." (PMID 35267530, 2022).
chronic myelogenous leukemia (2 papers, 2021 to 2024). "Although little is known about the function of PRDM12 in oncogenesis, previous studies showed that PRDM12 might act as a tumor suppressor gene in human chronic myeloid leukemia (CML)." (PMID 34769459, 2021).
clear cell renal cell carcinoma (2 papers, 2021 to 2022). "MTUS1, a tumour-suppressor gene encoding angiotensin-II type 2 receptor-interacting proteins, is downregulated in clear cell renal cell carcinoma." (PMID 34980126, 2022). "Previous studies have shown that is an innate immunity gene and involved in the development of eczema, clear cell renal cell carcinoma, meningioma, and childhood leukemia." (PMID 33579299, 2021).
colitis (2 papers, 2024 to 2025). Inflammation of the colon. "At the same time, the antimicrobial peptide activates the expression of the wnt frizzled gene in the wnt pathway, promotes the generation of intestinal stem cells, promotes the differentiation and repair of intestinal epithelial cells, and prevents colitis." (PMID 38254536, 2024).
depression (2 papers, 2025). "Over-expression of NEGR1, a synapse-adhesion gene highlighted by psychiatric GWAS, induces depression-like behaviour and impairs myelination; knocking it down rescues stress-induced anhedonia, revealing a fresh therapeutic target for synaptic repair." (PMID 41373485, 2025).
Fanconi anemia (2 papers, 2021). Fanconi anemia (FA) is a hereditary DNA repair disorder characterized by progressive pancytopenia with bone marrow failure, variable congenital malformations and predisposition to develop hematological or solid tumors. "Other candidate genes with known roles for CSAs included GTF2H (general transcription factor IIH subunits 4 and 5), Fanconi anemia pathway genes, and PMS2, a mismatch repair gene." (PMID 34220964, 2021).
Intellectual disability (2 papers, 2022 to 2024). "FXR1 on the other hand is an RNA-binding protein and ortholog of the fragile X and mental retardation gene FMR1." (PMID 35666183, 2022).
muscular dystrophy (2 papers, 2013 to 2021). Muscular dystrophy (MD) refers to a group of more than 30 genetic diseases characterized by progressive weakness and degeneration of the skeletal muscles that control movement. "Expression of the Duchenne muscular dystrophy gene (Dmd) was detectable only in MEFs, which can be induced to differentiate into myotube-like cells under different conditions." (PMID 23451074, 2013).
non-melanoma skin carcinoma (2 papers, 2015 to 2024). "We speculate that lincRNA-p21 may function as a tumor suppressor gene in UVB-induced non-melanoma skin cancer where the loss of lincRNA-p21 expression results in the evasion of apoptosis." (PMID 25789975, 2015).
Parkinson disease (2 papers, 2013 to 2022). A progressive degenerative disorder of the central nervous system characterized by loss of dopamine producing neurons in the substantia nigra and the presence of Lewy bodies in the substantia nigra and locus coeruleus. "Remarkably, djr-1.1 and djr-1.2 are homologs of the Parkinson’s disease-associated human gene DJ-1, also known as PARK7." (PMID 24324795, 2013).
sarcoma (2 papers, 2015 to 2023). A usually aggressive malignant neoplasm of the soft tissue or bone. "To further test the functional significance of miR-16 as a metastasis suppressor gene, we used a loss-of-function approach in primary sarcomas." (PMID 26044957, 2015).
Stroke (2 papers, 2017 to 2024). Sudden impairment of blood flow to a part of the brain due to occlusion or rupture of an artery to the brain. "The concentration of related proteins in the serum of stroke patients was determined by ELISA, and the patients were divided into groups to evaluate the effect of the ribosome biogenesis gene on patients." (PMID 39290696, 2024).
T cell lymphomas (2 papers, 2016 to 2023). "Thus, consistent with heterozygous mutations of Dnmt3a found in human T cell malignancies, Dnmt3a is a haploinsufficient tumor suppressor gene in the prevention of mouse mature CD8+CD4- T cell lymphomas." (PMID 27690235, 2016). "Kcnj16 is frequently mutated in T-cell lymphoma in mice lacking the DNA mismatch repair gene Mlh1, but its function in T-cell lymphoma remains unclear." (PMID 36923292, 2023).
abscess (1 paper, 2022). An inflammatory process characterized by the accumulation of pus within a newly formed tissue cavity which is the result of a bacterial, fungal, or parasitic infection or the presence of a foreign body. "Gene sdrD (serine–aspartate repeat protein D) is member of the MSCRAMMs (microbial surface components recognizing adhesive matrix molecules), promotes the adherence of S. aureus to nasal epithelial cells, human keratinocytes, and contributes to abscess formation." (PMID 36009880, 2022).
adenoma (1 paper, 2023). A neoplasm arising from the epithelium. "The genes CA2, CA7, and ITM2C collectively play critical roles in CRC progression, with CA2 influencing adenoma characteristics and cell proliferation, CA7 acting as a tumor suppressor gene, and ITM2C likely sharing similar tumor-suppressive properties with its family member ITM2A." (PMID 37895185, 2023).